RMEL3 (enriched in melanoma 3)
Gene: Long non-coding RNA gene on chromosome 5 (57,395,060 to 57,534,504, forward strand). Ensembl gene ENSG00000250961.
Diseases named in the same sentence as RMEL3 in open-access papers:
RMEL3 is named in the same sentence as 6 diseases in open-access papers, as found by Europe PMC text mining. Sharing a sentence is not in itself a finding about the gene and the disease. The quoted sentences say what the papers report.
melanoma (7 papers, 2010 to 2024). A malignant, usually aggressive tumor composed of atypical, neoplastic melanocytes. "It has been determined that RMEL3 is a melanoma-controlled lncRNA whose activity is strongly associated with mutations in BRAFV600E and NRASQ61L." (PMID 39777348, 2024). "Analysis of melanoma cells also suggested a positive correlation between RMEL3 expression and the presence of the BRAFV600E mutation." (PMID 27167340, 2016). "In conclusion, this work provides strong evidence that RMEL3, initially implicated by its specificity to melanoma, can affect malignancy through MAPK and PI3K stimulation." (PMID 27167340, 2016). "Analysis of The Cancer Genome Atlas (TCGA) data confirmed RMEL3 enriched expression in melanoma and demonstrated its association with the presence of BRAFV600E." (PMID 27167340, 2016). "We analyzed the publicly available melanoma TCGA data to identify significant clinical and molecular associations of RMEL3 expression." (PMID 27167340, 2016). "On the other hand, RMEL3 exhibited the inverse expression pattern, marked by relatively high levels in nevi and progressive loss during melanoma progression, as revealed by its loss in 31% of the primary tumors and in 88% of the metastatic tumors." (PMID 20975957, 2010). "RMEL3 knockdown in BRAFV600E melanoma cells of the A375-SM cell line reduced colony formation and caused an accumulation of cells in the G1 phase together with an increase in apoptosis." (PMID 28415644, 2017). "All but one (GAS5) of 13 lncRNAs reviewed are upregulated in melanoma compared with normal tissue, and three lncRNAs are suggested to be melanoma specific (RMEL3, SAMMSON, LLME23)." (PMID 28415644, 2017). "RMEL3 siRNA-mediated silencing markedly reduced (95%) colony formation in different BRAFV600E melanoma cell lines." (PMID 27167340, 2016). "RMEL3 knockdown in BRAFV600E melanoma cells, such as the A375-SM cell line, which has high RMEL3 expression, markedly reduced colony formation." (PMID 27167340, 2016). "In this work we confirmed previous findings of our group that RMEL3 is highly restricted to melanoma." (PMID 27167340, 2016). "Microarray analysis was performed following RMEL3 knockdown in the human melanoma cell line A375-SM to functionally validate genes regulated by RMEL3." (PMID 27167340, 2016). "Consistently RMEL3 knockdown induced a potent blockage over BRAFV600E melanoma cell growth and survival." (PMID 27167340, 2016). "RMEL3 mRNA expression was detected in 13 out of 19 melanoma cell lines and in low levels in two normal bladder samples and one prostate tumor." (PMID 20975957, 2010). "In BRAFV600E melanoma cell lines, RMEL3 depletion considerably decreases colony-forming potential." (PMID 39777348, 2024). "Interestingly, RMEL3 was significantly higher in BRAFmt melanoma compared to triplewt (RAS/BRAF/NF1) melanoma and expression levels were negatively correlated with melanoma progression." (PMID 28350340, 2017). "Previous work identified RMEL3 as a lncRNA with enriched expression in melanoma." (PMID 27167340, 2016). "RMEL3 expression was also significantly increased in melanomas with a BRAFV600E mutation compared to those with a wild type BRAF or triple wild type for BRAF/RAS/NF1, an association also observed in a panel of human melanoma cell lines." (PMID 27167340, 2016). "RMEL3 knockdown in A375-SM melanoma cells altered a total of 91 proteins (p<0.05)." (PMID 27167340, 2016). "In clinical samples representing melanoma progression [primary tumors (n=102), subcutaneous tumors (regional cutaneous and in-transit metastasis, n=74), regional lymph node (n=221) and distant metastasis (n=68)], RMEL3 expression was increased in subcutaneous tumors compared to primary tumors." (PMID 27167340, 2016). "Also, RMEL3 expression is significantly greater in melanoma than a diversity of other tumors." (PMID 27167340, 2016).
melanoma (continued). "In melanoma, a few lncRNAs have been identified such as SAMMSON, RMEL3, and LLME23, which are expressed in more than 90% of melanoma subtypes." (PMID 37509693, 2023). "Analysis of RNA expression data from 472 TCGA melanomas, 16 normal tissues (from Illumina Body Map Project) and 2 melanocytes (GSE38495) confirmed significantly increased expression of RMEL3 in the tumors." (PMID 27167340, 2016). "Previous work from our laboratory identified RMEL3 (ENSG00000250961) as a potential lncRNA with extremely enriched and specific expression in melanoma." (PMID 27167340, 2016). "Finally, BRAFV600E melanoma cells treated with BRAF or MEK inhibitors significantly decreased RMEL3 expression levels, suggesting RMEL3 as a downstream effector of ERK signaling and as a promising candidate for pharmacological target." (PMID 33503876, 2021). "Thus, TCGA data and functional experiments demonstrate that RMEL3 is required for MAPK and PI3K signaling, and its knockdown decrease BRAFV600E melanoma cell survival and proliferation." (PMID 27167340, 2016). "This study supports that RMEL3 knockdown inhibits MAPK and PI3K pathways in melanoma." (PMID 27167340, 2016). "Because RMEL3 depletion decrease cell survival and proliferation in BRAFV600E melanoma cell lines, it might represent a potential therapeutic target gene in this subset of melanomas." (PMID 28350340, 2017). "Thus, we suggest that future investigation will be worthwhile to assess the relevance of RMEL2 expression as a marker to predict disease outcome in lymph node-negative patients and RMEL3 as a general marker of melanoma patient outcome." (PMID 20975957, 2010). "However, RMEL3 experiments could not confirm these clinical findings and suggested that RMEL3 plays a pro-oncogenic role, since knockdown experiments resulted in a 95% decrease of colony formation in different BRAFV600E melanoma cell lines." (PMID 28350340, 2017).
metastatic tumors (1 paper, 2010). "RMEL3 showed strong up-regulation in nevi and was lost in metastatic tumors." (PMID 20975957, 2010).
ovarian carcinoma (1 paper, 2016). A malignant neoplasm originating from the surface ovarian epithelium. "In contrast, SKOV3 ovarian cancer cell line, which has no RMEL3 expression, was not affected, demonstrating that the observed effects were not due to siRNA overall cytotoxicity or non-specific targeting." (PMID 27167340, 2016).
cancer (2 papers, 2016 to 2024). A tumor composed of atypical neoplastic, often pleomorphic cells that invade other tissues. "RMEL3 is involved in protein kinase A signaling, molecular mechanisms of cancer, regulation of epithelial-mesenchymal transition, matrix metalloprotease protection, in addition to the ability to promote malignancy." (PMID 38397135, 2024). "Pathway enrichment analysis of the validated genes implicates RMEL3 in protein kinase A signaling, molecular mechanisms of cancer, FGF signaling, regulation of epithelial-mesenchymal transition, inhibition of matrix metalloproteases, among others." (PMID 27167340, 2016).
tumor (1 paper, 2010). "RMEL3 shows an intriguing expression profile, suggestive of a possible role for this gene in nevi and as a tumor or metastasis suppressor." (PMID 20975957, 2010). "Interestingly, we found correlations of RMEL2 and RMEL3 expression with improved patient outcome, suggesting tumor and/or metastasis suppressor functions for these genes." (PMID 20975957, 2010). "Survival curves calculated using Kaplan-Meier method show that lack of RMEL3 expression in the tumor correlates with poor survival rates, with most deaths occurring within 2.2 years of follow up, an interval in which all ten patients with detectable expression were still alive." (PMID 20975957, 2010). "Compatible with a protective role for RMEL3, we observed correlation of expression with the absence of lymph vascular invasion in the primary tumor site (10/11 patients), while in contrast only 1 of 4 patients lacking RMEL3 expression showed no lymph vascular invasion (p = 0.002)." (PMID 20975957, 2010).
RMEL3 also shares sentences with these, for which no sentence is quoted: prostate tumor (1 paper).